SAT1 (spermidine/spermine N1-acetyltransferase 1)
Diseases named in the same sentence as SAT1 in open-access papers (continued):
Sharing a sentence is not in itself a finding about the gene and the disease.
movement disorder (1 paper, 2020). Neurological conditions resulting in abnormal voluntary or involuntary movement, which may impact the speed, fluency, quality and ease of movement. "The Smox-KO, Sat1-KO, and Wt did not develop any movement disorders and did not have increased mortality or weight loss that required them to be euthanized." (PMID 33054763, 2020).
neurodegenerative disease (1 paper, 2020). A disorder of the central nervous system characterized by gradual and progressive loss of neural tissue and neurologic function. "Given the role of TGMs in neurodegenerative diseases and their ability to polyaminate proteins, we assessed if there were alterations in protein polyamination in the cerebellum of Smox/Sat1-dKO mice." (PMID 33054763, 2020).
SAT1 also shares sentences with these, for which no sentence is quoted: melanoma (4 papers); breast tumor (3); mental disorder (3); cervical cancer (2); leukaemia (2); myocardial ischemia (2); non-small cell lung carcinoma (2); ovarian carcinoma (2); pancreatitis (2); schizophrenia (2); triple-negative breast carcinoma (2); acute myeloid leukemia (1); adult-onset Still disease (1); allergic reactions (1); autism (1); benign prostatic hyperplasia (1); bipolar disorder (1); cardiomyopathy (1); Cognitive impairment (1); epilepsy (1); gastrointestinal tract cancers (1); Glucose intolerance (1); heart failure (1); Hypertension (1); hyperthyroidism (1); idiopathic cardiomyopathy (1); infertile (1); injury (1); intestinal cancer (1); intestinal tumor (1).
A further 30 diseases each share a sentence with SAT1 in 1 paper.